CSF3 (colony stimulating factor 3)
Diseases named in the same sentence as CSF3 in open-access papers (continued):
Sharing a sentence is not in itself a finding about the gene and the disease.
lung fibrosis (15 papers, 2019 to 2025). "Recombinant CSF3 promoted myofibrogenesis in lung fibroblasts, whereas CSF3-deficient mice were protected from bleomycin-induced pulmonary fibrosis." (PMID 41034234, 2025). "We demonstrated that the loss of CSF3 function, achieved through neutralizing antibody treatment or gene expression depletion, can prevent and restore the development of pulmonary fibrosis in mouse models." (PMID 41034234, 2025). "For example, lung fibrosis-associated genes (CSF3, IL8, CSF2, IL6, TNF, MMP9, IL1B and PDGFB) were significantly upregulated in SARS-CoV-2-infected NHBE cells." (PMID 32698440, 2020). "Collectively, these findings provide compelling evidence that CSF3 plays a crucial role in the progression of pulmonary fibrosis." (PMID 41034234, 2025). "In conclusion, our study identifies CSF3 as a critical cytokine involved in the initiation, progression, and maintenance of pulmonary fibrosis." (PMID 41034234, 2025). "In contrast, knockout of the CSF3 gene confers protection against bleomycin-induced lung fibrosis, suggesting that CSF3 is integral to the fibrotic response." (PMID 41034234, 2025). "Our data provide compelling evidence that CSF3 is a crucial mediator of pulmonary fibrosis progression." (PMID 41034234, 2025). "To investigate the role of CSF3 in pulmonary fibrosis, we used a CSF3 knockout (KO) mouse model and administered BLM via intratracheal injection." (PMID 41034234, 2025). "To evaluate the therapeutic potential of neutralizing CSF3 in pulmonary fibrosis, we developed a CSF3-neutralizing antibody, FB-101, and assessed its efficacy in two distinct BLM-induced IPF mouse models." (PMID 41034234, 2025). "In the BLM-induced mouse model of pulmonary fibrosis, increased CSF3 expression was also demonstrated in lung tissues via IHC staining." (PMID 41034234, 2025). "Furthermore, CSF3 acts as a key effector in the progression of pulmonary fibrosis induced by TGF-β." (PMID 41034234, 2025). "The positive feedback loop between CSF3 and TGF-β appears to constitute a central pathway that regulates both the initiation and progression of pulmonary fibrosis." (PMID 41034234, 2025). "Our analysis showed that eight genes (CSF2, CSF3, CXCL2, CXCL8, IL1B, IL6, MMP9, and TNF) are significantly overlapping with the lung fibrosis pathway with p-value 9.35e-11." (PMID 33362771, 2020). "In addition, CSF3 expression was significantly higher in lung tissue from IPF patients compared to control, as confirmed by immunohistochemical (IHC) staining of pulmonary fibrosis tissue arrays." (PMID 41034234, 2025). "CSF3 probably counteracts fibrosis, as high expression levels have been correlated with reduced ECM deposition in the liver, and its administration in bleomycin-affected mice resulted in the amelioration of pulmonary fibrosis." (PMID 36632136, 2022). "Given the crucial role of TGF-β1 in pulmonary fibrosis, including its involvement in EMT, fibroblast-to-myofibroblast transition (FMT), ECM deposition, and myofibroblast activation, we aimed to investigate the relationship between CSF3 and TGF-β1 in IPF pathogenesis." (PMID 41034234, 2025). "Importantly, the expression of CSF3 was correlated with genes involved in ECM remodeling and fibrogenesis, suggesting that CSF3 plays a pivotal role in the development and progression of pulmonary fibrosis." (PMID 41034234, 2025). "Furthermore, the administration of CSF3-neutralizing antibodies resulted in a notable reversal of pulmonary fibrosis in IPF mouse models, supporting the hypothesis that CSF3 is a central mediator in the development and maintenance of fibrosis." (PMID 41034234, 2025).
periodontitis (15 papers, 2016 to 2026). An acute or chronic inflammatory process that affects the tissues that surround and support the teeth. "Previous studies have demonstrated that CSF3 release in bone tissue disrupts the balance between bone formation and resorption, leading to pathological conditions associated with excessive bone resorption, such as periodontitis and osteoporosis." (PMID 40332455, 2025). "For example, the levels of IL-33 and granulocyte colony-stimulating factor (G-CSF), encoded by the CSF3 gene, are increased in mice with experimentally induced periodontitis and in gingival epithelial cells from periodontitis patients." (PMID 36776856, 2023). "Out of the 20 most upregulated genes in periodontitis tissues compared to controls, five were induced in DAC-treated GFs in our experiments (CSF3, GLDC, SAA1, SAA2, GDF15), highlighting the notion that DNMT inhibitors upregulate several genes that are associated with periodontitis pathology." (PMID 36776856, 2023). "CSF3, ICAM2, and MMP7 serve as diagnostic and prognostic biomarkers for periodontitis." (PMID 36457739, 2022). "CXCL1, CXCL3, CXCL8, CSF3, IL1A, IL1B, and IL1RN all increased in JKs in periodontitis as predicted by our atlas/DEG analyses; alternatively, SKs were relatively less active compared to JKs." (PMID 38876998, 2024). "One study identified several biomarkers using bioinformatics analysis, such as CSF3, CXCL12, IL-1B, MS4A1, PECAM1, and TAGLN, and they all served as predictors of diagnosis and prognosis in chronic periodontitis." (PMID 36457739, 2022).
coronary artery disease (12 papers, 2009 to 2025). "CSF3, IL-1A, CCR7, IL-18, and MAPK14, as well as IL-17 signaling pathway and cytokine and cytokine receptor interaction signaling pathway related with inflammatory response might be the potential biomarker and targets for the treatment of coronary artery disease." (PMID 33777109, 2021).
Allergy (11 papers, 2005 to 2024). An allergy is an immune response or reaction to substances that are usually not harmful. "The analysis implicated a number of genes with roles in allergy and inflammation, including pro-inflammatory cytokines (IL1A, IL1B, IL6, IL8 and TNF) and factors involved in immune cell activation and recruitment (SELE, SELL, SELP, ICAM1, CSF2, CSF3, CCL2 and CXCL2)." (PMID 21067579, 2010).
endometriosis (11 papers, 2016 to 2025). The growth of functional endometrial tissue in anatomic sites outside the uterine body. "CSF3 down-regulation by elagolix is also interesting, as it has been shown to be higher in PF of women with endometriosis." (PMID 38999962, 2024).
tuberculosis (11 papers, 2015 to 2025). A chronic, recurrent infection caused by the bacterium Mycobacterium tuberculosis. "However, IL-10 may be involved in the mutual regulation of the levels of CSF-2 and CSF-3 to balance the levels of these three cytokines, which is associated with the risk of tuberculosis." (PMID 37818041, 2023). "We performed cluster analysis for the top 5 KEGG pathways to explore the association of genes such as LBP, CSF3, and FCGR2A with leishmaniasis, hematopoietic cell, strain, tuberculosis, and osteoclast differentiation." (PMID 33973530, 2021). "Percentages of IL-6+ and TNF-α+ neutrophils were lower in HIV-tuberculosis patients (q = 0.01 and q = 0.07, respectively), whereas concentrations of CSF-3, IFN-ɣ, and IL-1RA were higher." (PMID 28369200, 2017). "HIV-tuberculosis patients had higher supernatant concentrations of CSF-3, IFN-ɣ, and IL-1-receptor-antagonist (IL-1RA) and lower concentrations of CSF-2, IL-12p40, IL-1β, IL-6, and TNF-α." (PMID 28369200, 2017). "The expression levels of certain genes related to anti-tuberculosis were further confirmed, such as CCL1, IL15, IL16, ISG15, GBP5, IL23, ATG2A, IFNβ, and CSF3." (PMID 38392218, 2024). "Rv1476 overexpression inhibited the expression of some anti-tuberculosis-related genes, such as CCL1, IL15, IL16, ISG15, GBP5, IL23, ATG2A, IFNβ, and CSF3." (PMID 38392218, 2024). "Subsequently, we further verified the transcription levels of genes on anti-tuberculosis-related genes such as CCL1, IL15, IL16, ISG15, GBP5, IL23, ATG2A, IFNβ, and CSF3." (PMID 38392218, 2024). "Our data of increased, rather than decreased, concentrations of CSF-3 in patients who die do not support investigation of CSF-3 for host-directed therapy in HIV-tuberculosis." (PMID 28369200, 2017). "In unstimulated samples, patients with HIV-tuberculosis had higher percentages of tumor necrosis factor (TNF)-α+ monocytes compared with controls and higher supernatant concentrations of colony-stimulating factor (CSF)-3 and IFN-ɣ, whereas supernatant concentrations of IL-1β and IL-8 were lower." (PMID 28369200, 2017).
chorioamnionitis (10 papers, 1995 to 2025). A morphologic finding indicating inflammation of the fetal sac membranes. "The amnion secretes IL-1 during chorioamnionitis, which causes neutrophil accumulation via up-regulating the production of IL-8/CXCL8 and GCSF/CSF3." (PMID 37475854, 2023).
glioblastoma (10 papers, 2014 to 2024). The most malignant astrocytic tumor (WHO grade IV). "Using transcriptomic data from the BELOB phase II trial, which compared lomustine versus lomustine plus bevacizumab in recurrent glioblastoma, we confirmed that CSF3 expression was overexpressed in mesenchymal tumors and correlated with VEGFA expression (see eFigure 5 in the Supplement)." (PMID 27487142, 2016). "Using public transcriptomic data from The Cancer Genome Atlas for 202 patients suffering from GBM, we found that CSF3 was overexpressed mostly in mesenchymal glioblastoma." (PMID 27487142, 2016). "The correlation between GCSF (CSF3) and GCSFR (CSF3R) was analyzed, and highly correlate in glioblastoma patients with an optimum cut-off median at significance level p = 0.05." (PMID 38538691, 2024).
myeloproliferative disease (10 papers, 2010 to 2025). "Chronic neutrophilic leukemia (CNL) is a myeloproliferative neoplasm characterized by the overproduction of neutrophils and activating mutations in CSF3R, the receptor for colony stimulating factor 3 (GCSF)." (PMID 35200567, 2022).
granulocytosis (9 papers, 2010 to 2022). "We eliminated any increase in the key growth factor, CSF3, as a mechanism underlying granulocytosis." (PMID 34081701, 2021).
osteoporosis (9 papers, 2010 to 2025). A condition of reduced bone mass, with decreased cortical thickness and a decrease in the number and size of the trabeculae of cancellous bone (but normal chemical composition), resulting in increased fracture incidence. "The interaction of PROK2 and CSF3, core genes related to osteoporosis inflammation, plays an important role in the mechanism of osteoporosis in patients with Alzheimer's." (PMID 36203970, 2022). "In the GSE62402 dataset, related to osteoporosis, two differentially expressed mRNAs, Prokineticin 2 (PROK2) and Colony Stimulating Factor 3 (CSF3), were identified." (PMID 40153574, 2025).
Parkinson disease (9 papers, 2009 to 2024). A progressive degenerative disorder of the central nervous system characterized by loss of dopamine producing neurons in the substantia nigra and the presence of Lewy bodies in the substantia nigra and locus coeruleus. "The results showed that the top four positive regulatory pathways of CSF3 were proteasome, Parkinson’s disease, oxidative phosphorylation, and Graft vs. host disease." (PMID 33551833, 2020). "It was reported that peripheral treatment of CSF3 showed neuroprotective characteristics in models of TBI, Parkinson’s disease, and carbon monoxide poisoning." (PMID 37901226, 2023).
bone cancer (8 papers, 2006 to 2025). A primary or metastatic malignant neoplasm affecting the bone or articular cartilage. "CSF3 has been reported to sensitize nerves to mechanical stimuli in the skin, and the interruption of CSF3 signaling could reduce bone cancer pain." (PMID 35281296, 2022).
brain injury (8 papers, 2011 to 2024). Acute and chronic (see also brain INJURIES, CHRONIC) injuries to the brain, including the cerebral hemispheres, CEREBELLUM, and brain STEM. "Furthermore, we found that the potent neuroprotective agent CSF3 attenuates neuroinflammation and neuronal apoptosis by modulating inflammatory and apoptotic mediators and promotes neurogenesis and angiogenesis, thereby playing a neuroprotective role in childhood brain injury." (PMID 36425058, 2022).
head and neck squamous cell carcinoma (8 papers, 2012 to 2025). A squamous cell carcinoma that arises from any of the following anatomic sites: lip and oral cavity, nasal cavity, paranasal sinuses, pharynx, larynx, and salivary glands. "In NFE2L2‐mutated head and neck squamous cell carcinoma, CSF3 recruits MDSCs to mediate chemotherapy resistance." (PMID 37666495, 2024).
E. coli infection (7 papers, 2019 to 2025). "Also, CSF3 has been shown to induce the migration of neutrophils which have a key role in bacterial clearance during pathogenic E. coli infection." (PMID 40141330, 2025). "A plausible anti-inflammatory effect of EPS was observed in this study, as the expression of the IL12B, TNF, CSF1 and CSF3 genes was abated in the cells pretreated before E. coli infection." (PMID 32234079, 2020).
lung adenocarcinoma (7 papers, 2022 to 2025). A carcinoma that arises from the lung and is characterized by the presence of malignant glandular epithelial cells. "Analyses of TCGA data to correlate prognosis with cytokine mRNA expression in lung adenocarcinoma patients identified increased levels of the mRNAs for Csf3, Cxcl1, and IL-6 as significant indicators of a worse prognosis." (PMID 39338937, 2024). "We found CD1A|CXCL13, CD1A|S100A7L2, IFNA7|CMTM2, IFNA7|CSF3, CAMP|TFR2, this 5‐IRGPs were strongly associated with the prognosis of patients, all of which were protective factors for the prognosis of lung adenocarcinoma." (PMID 35246970, 2022). "Among the top three significantly dysregulated genes, CSF3 exhibited significant dysregulation in tumor samples from both lung adenocarcinomas and lung squamous cell carcinomas cases compared to controls, with statistical significance (p < 0.05, independent t-test)." (PMID 40797277, 2025). "Among these, CSF3 and GABBR1 showed significantly reduced expression in lung adenocarcinoma tissues compared to normal tissues." (PMID 39727962, 2024).
mastitis (7 papers, 2016 to 2025). Inflammation of breast tissue during lactation or postpartum due to an obstructed duct or infection. "In contrast, introgressed regions contained STAT5A and CSF3, both associated with mastitis resistance in cattle, and genes (CX3CR1 and CSF3) and QTLs involved in immune response and parasite resistance." (PMID 41273432, 2025). "In contrast, introgressed regions contain STAT5A and CSF3, both associated with mastitis resistance in cattle, the latter being also linked to gastrointestinal nematode resistance." (PMID 41273432, 2025). "The results from this study may candidate CSF3 as a biomarker of the mastitis in buffalo." (PMID 39858163, 2025).
bone marrow failure (5 papers, 2009 to 2023). "However, upon stratification of DC patients based on the presence of severe bone marrow failure, significant levels of CSF3 (G-CSF) were found, consistent with our results." (PMID 37717172, 2023).
encephalitis (5 papers, 2016 to 2023). An acute inflammatory process affecting the brain parenchyma. "For LGI1 encephalitis patients (n = 6) and HDs (n = 4), miR-2467-5p expression in PBMCs was negatively associated with the serum levels of PDCD1 (r = −0.867, p = 0.002) and CSF3 (r = −0.721, p = 0.023), but favorably correlated with the serum level of CCL15 (r = 0.746, p = 0.017)." (PMID 37644514, 2023). "Significant methylation alterations were found in the promoters of CSF3, CCL2, and ICAM1 in LGI1 encephalitis patients comparable to healthy individuals." (PMID 37644514, 2023). "Mechanically, miR-2467-5p significantly induced reduced expression of CSF3 and PDCD1 by binding with their 3`UTR while enhanced CCL15 expression, but not significantly correlated with peripheral blood CD19 + B cell proportion of LGI1 encephalitis patients." (PMID 37644514, 2023). "Then, bioinformatics algorithms uncovered the probable miR-2467-5p binding sites in the 3'untranslated region (UTR) of CSF3' and PDCD1' mRNA, and a negative correlation was found between PDCD1 expression and CCL15 expression in the serum of LGI1 encephalitis patients (r = −0.546, p = 0.013)." (PMID 37644514, 2023).
glomerulonephritis (5 papers, 2018 to 2022). A renal disorder characterized by damage in the glomeruli. "Granulocyte colony-stimulating factor (G-CSF; also known as colony stimulating factor 3) is produced from monocytes and macrophages during inflammation, and their infiltration is observed in human glomerulonephritis." (PMID 31270736, 2020).
gout (4 papers, 2020 to 2025). A condition characterized by painful swelling of the joints, which is caused by deposition of urate crystals. "G-CSF, a 25 kDa glycoprotein encoded by the CSF3 gene, emerges as a pivotal orchestrator of neutrophilic inflammation in gout pathogenesis." (PMID 40388724, 2025).
rectal cancer (4 papers, 2008 to 2022). A primary or metastatic malignant neoplasm that affects the rectum. "The same approach for both colon and rectal cancers could be used to direct future studies of CSF3 and CSF3R involvement in tumor development and progression." (PMID 33606788, 2021).
sarcoidosis (4 papers, 2020 to 2025). Sarcoidosis is a multisystemic disorder of unknown cause characterized by the formation of immune granulomas in involved organs. "Eight upregulated transcripts were common to sarcoidosis lung granulomas (CSF3, SERTAD1, MMP9, CCL19, BCL3, AREG, PTGS, F3)." (PMID 33276795, 2020). "Among the twelve common DEGs, SALL4, WNT10A, RASAL1, CAMK2B were significantly upregulated while GADD45B, KLF4, OLR1, CSF3, WIF1, RAMP3 and AGER downregulated in both sarcoidosis and LC as compared to the controls." (PMID 40797277, 2025).
allergic asthma (3 papers, 2012 to 2025). A asthma with a basis in a pathological type I hypersensitivity reaction. "In Csf3-/-mice, OVA could induce allergic asthma characterized by eosinophilic airway inflammation and airway hyperresponsiveness." (PMID 40963601, 2025).
keloid (3 papers, 2022 to 2023). An irregularly shaped, elevated mark on the skin caused by deposits of excessive amounts of collagen during wound healing. "Furthermore, we found that differentiation of IL6+CSF3+ activated endothelial cells to MMP1+ endothelial cells activated by the NFΚB signaling pathway is a major feature of keloid vascular lesions." (PMID 36082167, 2022). "We identified four subpopulations of endothelial cells in keloid and normal scar tissue by scRNA-seq data: MMP1+ Endo0, FOS + JUN + Endo1, IL6+CSF3+ Endo2, CXCL12 Endo3." (PMID 36082167, 2022).
nonalcoholic fatty liver disease (3 papers, 2022 to 2024). "In addition, the CSF3/CSF3R axis is involved in lipid metabolism and promotes the development of nonalcoholic fatty liver disease and AS29,30." (PMID 38503760, 2024).
Parasite infection (3 papers, 2010 to 2024). "KEGG enrichment analysis again enriched various pathways, including “Signaling by CSF3 (G-CSF),” “RHO GTPases Activate NADPH Oxidases,” “Regulation of signaling by CBL,” “Parasite infection,” “Neutrophil degranulation,” “Leishmania phagocytosis,” “Leishmania infection,” “Interleukin-3." (PMID 38629070, 2024).
Salmonella Infections (3 papers, 2011 to 2023). Infections with bacteria of the genus SALMONELLA. "HIO production of IL17C and its known downstream proinflammatory mediators, including CSF3 and DEF4BA, also suggest that IL17C signaling modulates human intestinal host defense against Salmonella infection." (PMID 34669717, 2021).